EFEMP1 (EGF-like fibulin extracellular matrix protein 1)
Diseases named in the same sentence as EFEMP1 in open-access papers (continued):
Sharing a sentence is not in itself a finding about the gene and the disease.
Hypertension (4 papers, 2022 to 2024). The presence of chronic increased pressure in the systemic arterial system. "Increased levels of EGF-containing fibulin-like extracellular matrix protein 1 (EFEMP1), also known as fibulin 3, have been shown to reduce vascular remodeling and oxidative stress in hypertension and slow down vascular smooth cell calcification." (PMID 39546296, 2024).
liver cancer (4 papers, 2011 to 2024). An epithelial or non-epithelial malignant neoplasm that arises from the liver. "Subsequently, we detected the expression of EFEMP1 in normal liver cell L02 and liver cancer cell lines HepG2 and Huh7." (PMID 30972979, 2019). "Therefore, to further verify the effect of EFEMP1 on the proliferation of liver cancer cells as reflected in the MTT assay results, cell clonal formation experiment was performed." (PMID 30972979, 2019). "Subsequently, the colony formation assay reflected that overexpression of EFEMP1 could inhibit the colony formation of liver cancer cell." (PMID 30972979, 2019). "The previous results suggested that the expression of EFEMP1 was inhibited in liver cancer." (PMID 30972979, 2019). "We used real‐time polymerase chain reaction (RT‐PCR) to detect the mRNA level of EFEMP1 in 30 pairs of human liver cancer tissues and adjacent noncancerous tissues." (PMID 30972979, 2019).
liver disease (4 papers, 2018 to 2025). "It was found that the staining intensity and positive rate of EFEMP1 gradually decreased with the severity of liver disease." (PMID 30972979, 2019). "In conclusion, the chip results suggest that EFEMP1 was involved in the process of liver disease, and its expression was significantly reduced during hepatocarcinogenesis." (PMID 30972979, 2019). "The results suggested that EFEMP1 may be involved in the process of liver disease." (PMID 30972979, 2019). "In addition, many novel liver disease biomarkers were discovered, such as EGF-containing fibulin-like extracellular matrix protein 1 (EFEMP1), SAA2, CPN2, ANPEP, TGFBI, and FGG." (PMID 37209815, 2023).
myopia (4 papers, 2023 to 2024). "For myopia, EFEMP1 is highly expressed in the corneal and choroidal retinal pigment epithelium and is a potential biomarker of choroid thickness changes in myopia." (PMID 39408566, 2024). "In addition, a recent reported case with biallelic EFEMP1 loss-of-function variants (c.320_324del, p.Met107fs; c.615T>A, p.Tyr205Ter) manifested connective tissue abnormalities, including tall stature, hernia, hypermobile joints, thin translucent skin, and importantly high myopia." (PMID 39607017, 2024). "Meanwhile, tears of patients with emmetropia and myopia were collected and analyzed, and EFEMP1 concentrations in tears were significantly increased." (PMID 36891459, 2023). "The average levels of EFEMP1 tears in the myopia group and the emmetropia group were 150.53 ± 42.37 ng/ml and 244.89 ± 51.35 ng/ml, respectively, with a significant difference between the two groups (p < 0.001)." (PMID 36891459, 2023). "EFEMP1 is typically characterized by a structural domain rich in epidermal growth factor (EGF), while EGF has been proven to be highly associated with myopia." (PMID 36891459, 2023). "Tear concentrations of EFEMP1 in the myopia group were negatively correlated with SE (r = −0.4800, p < 0.001), and AL (r = 0.5991, p < 0.001), ACD (r = 0.4175, p < 0.001), and AL/CR (r = 0.4639, p < 0.001) were positively correlated." (PMID 36891459, 2023). "Since CT depends on its perfusion rate, we speculate that EFEMP1 may act as a signaling molecule to regulate the alteration of CT in the development of myopia." (PMID 36891459, 2023). "EFEMP1 may be a potential target for the prevention and treatment of choroid thickness changes in myopia." (PMID 36891459, 2023). "We speculate that EFEMP1 may be involved in the development of myopia, especially in choroid thickness." (PMID 36891459, 2023). "Targeted regulation of EFEMP1 may be useful for investigating the molecular mechanism of CT changes during myopia development." (PMID 36891459, 2023). "Combined with the decrease in choroid thickness in myopic patients and the significant increase in EFEMP1 concentrations in the tears of myopic patients in this study, we speculated that EFEMP1 might be involved in the molecular mechanism of CT changes during the development of myopia." (PMID 36891459, 2023). "Therefore, EFEMP1 may be involved in the regulation of choroidal thickness in myopia patients." (PMID 36891459, 2023). "Further investigation might target interactions between EFEMP1, WNT2B and EMT in myopia development." (PMID 39607017, 2024). "To date, whether the protein levels of EFEMP1 in the choroid change during the development of form-deprivation myopia (FDM) has not been reported." (PMID 36891459, 2023). "However, studies on changes in EFEMP1 protein in the choroid in myopia models have not been reported." (PMID 36891459, 2023).
retinal degeneration (4 papers, 2013 to 2022). Degeneration of the retina. "The development of AMD is associated with CFH (an inhibitor for alternative complement), EFEMP1 (a high-risk gene for AMD and other retinal degenerations), and VEGFA (a protein associated with increased choroidal neovascularization)." (PMID 36078063, 2022). "Q-PCR analyses showed J cybrids had decreased expressions for CFH, C3, and EFEMP1 genes, high risk genes for AMD, and higher expression for MYO7A, a gene associated with retinal degeneration in Usher type IB syndrome." (PMID 23365660, 2013).
retinal disease (4 papers, 2015 to 2024). "Apoptosis is also a characteristic hallmark of retinal diseases, so BBC3 and BCL2L13, RARA were investigated, as well as genes (EFEMP1, CFH) involved in the regulation of methylation sites." (PMID 36078063, 2022). "In conclusion, beyond retinal disease, our data support the notion that EFEMP1 is a plausible candidate gene for POAG." (PMID 26162006, 2015). "However, mice lacking EFEMP1 did not develop an obvious retinal pathology suggesting that deleterious gain-of-function mechanisms, rather than loss-of-function effects, trigger retinal disease." (PMID 26162006, 2015).
Werner syndrome (4 papers, 2013 to 2025). "Fibulin-3 (EFEMP1) was first found to be overexpressed in senescent human fibroblasts established from a Werner syndrome patient with premature aging." (PMID 30227601, 2018). "The glycoprotein fibulin-3 is also known as S15 or T16 or EFEMP1 (EGF-containing fibulin-like extracellular matrix protein 1) protein, and, for the first time, it has been observed in senescent human fibroblasts, established from a patient with Werner syndrome with premature aging." (PMID 34063320, 2021).
colon carcinoma (3 papers, 2015 to 2020). "Inactivation of EFEMP1 by promoter methylation is associated with lung, breast, liver, endometrial, prostate and colon cancers." (PMID 25987128, 2015). "However, the EFEMP1 levels in the serum and urine of patients with prostate and colon cancer are significantly lower compared with those of control subjects." (PMID 32280689, 2020). "In the HCT116 colon carcinoma cell line, EFEMP1 could promote growth, migration and invasion of cancer cells through a mechanism correlated to p38α and/or p38β activation." (PMID 27351229, 2016).
fibrosis (3 papers, 2023 to 2025). the formation of excess fibrous connective tissue in an organ or tissue in a reparative or reactive process. "For example, it has been reported that the level of mRNA that encodes for the EFEMP1 significantly correlates with fibrosis in nonalcoholic fatty liver disease patients, while the EFEMP1 protein can inhibit the proliferation, migration, and apoptosis of HCC cells." (PMID 37209815, 2023).
metastatic tumors (3 papers, 2015 to 2021). "In UBUC, 43 patients (29.1%) with high EFEMP1-expressing tumors experienced cancer deaths and 60 patients (40.5%) had subsequent metastatic tumors, whereas only 16 patients (10.9%) with low EFEMP1-expressing tumors had caner metastasis and nine patients (6.2%) died of the disease." (PMID 34204134, 2021).
non-small cell lung carcinoma (3 papers, 2013 to 2018). A group of at least three distinct histological types of lung cancer, including non-small cell squamous cell carcinoma, adenocarcinoma, and large cell carcinoma. "Downregulation of EFEMP1 was closely associated with promoter hypermethylation in breast, hepatocellular, colorectal, prostate and non-small cell lung carcinomas." (PMID 24345474, 2013). "In contrast, hypomethylation of EFEMP1 was identified as independent prognostic marker of non-small cell lung carcinoma (NSCLC)." (PMID 29851970, 2018).
Obesity (3 papers, 2021 to 2022). Accumulation of substantial excess body fat. "Some genes are also affected by rare CNVs in subjects with obesity, and thereby, this drives an alteration in gene expression of epidermal growth factor EFEMP1, which is involved in ECM remodeling in SAT, indicating that rare CNVs could be involved in the development of early-onset obesity." (PMID 33803198, 2021).
primary open angle glaucoma (3 papers, 2020 to 2023). "Previous studies have found that altered EFEMP1 expression is closely associated with many ocular diseases, mutations in EFEMP1 expression (R345 W) may lead to Malattia Leventinese, and the expression of EFEMP1 is abnormally high in the ciliary body of patients with open-angle glaucoma." (PMID 36891459, 2023).
pulmonary fibrosis (3 papers, 2022 to 2024). Chronic progressive interstitial lung disorder characterized by the replacement of the lung tissue by connective tissue, leading to progressive dyspnea, respiratory failure, or right heart failure. "An association between EFEMP1 single-nucleotide polymorphisms and constrictive lung disease including pulmonary fibrosis has also been reported." (PMID 38829196, 2024).
chronic obstructive pulmonary disease (2 papers, 2022 to 2025). A chronic and progressive lung disorder characterized by the loss of elasticity of the bronchial tree and the air sacs, destruction of the air sacs wall, thickening of the bronchial wall, and mucous accumulation in the bronchial tree. "Similarly, both proteins encoded by EFEMP1 and NPNT exhibited indirect effects on chronic obstructive pulmonary disease (COPD) by FEV1/FVC." (PMID 40136421, 2025).
fibrosarcoma (2 papers, 2015 to 2017). A malignant mesenchymal fibroblastic neoplasm affecting the soft tissue and bone. "Moreover, EFEMP1 blocks the migration of endothelial cells and hampers the proliferation of fibrosarcoma cell lines." (PMID 25987128, 2015).
late-onset retinal degeneration (2 papers, 2025). Late-onset retinal degeneration is an inherited retinal dystrophy characterized by delayed dark adaptation and nyctalopia and drusen deposits presenting in adulthood, followed by cone and rod degeneration that presents in the sixth decade of life, which leads to central vision loss. "These include Sorsby’s dystrophy (TIMP3 mutation), Doyne Honeycomb dystrophy (EFEMP1 mutation), and Late-Onset Retinal Degeneration (L-ORD, C1qTNF5 mutation)." (PMID 39983974, 2025).
Leber congenital amaurosis (2 papers, 2021 to 2025). Leber congenital amaurosis (LCA) is a retinal dystrophy defined by blindness and responses to electrophysiological stimulation (Ganzfeld electroretinogram (ERG)) below threshold, associated with severe visual impairment within the first year of life. "Vessel density was found to be highest in EFEMP1, BEST1, TIMP3, RS1, and PRPH2 (11.0%, 10.4%, 10.1%, 10.1%, 9.2%) and was lower in retinitis pigmentosa (RP) and Leber congenital amaurosis genes." (PMID 39896422, 2025).
lung diseases (2 papers, 2022 to 2025). "Firstly, in MR analysis between proteins and pulmonary diseases, three proteins, including EFEMP1, GM2A, and NPNT, were identified that exhibit a causal relationship with COPD while five proteins were highlighted that have causal effect on asthma." (PMID 40136421, 2025). "Subsequently, with these proteins related to pulmonary diseases, we found three potential mediation pathways including indirect effect of EFEMP1 on COPD via FEV1/FVC, an indirect effect of MAPK3 on Asthma via FEV1/FVC and an indirect effect of NPNT on COPD risk via FEV1/FVC." (PMID 40136421, 2025).
myocardial infarction (2 papers, 2023 to 2025). Gross necrosis of the myocardium, as a result of interruption of the blood supply to the area, as in coronary thrombosis. "Increased EFEMP1 expression has been reported in cardiac fibrosis, and it contributes to scar formation after myocardial infarction by participating in elastic fibre assembly and promoting inflammation." (PMID 40243889, 2025). "Fibulin-3 knockout (Efemp1−/−) and wildtype mice were subjected to experimental myocardial infarction." (PMID 37696945, 2023).
osteoporosis (2 papers, 2016 to 2020). A condition of reduced bone mass, with decreased cortical thickness and a decrease in the number and size of the trabeculae of cancellous bone (but normal chemical composition), resulting in increased fracture incidence. "The POP variants in and near to EFEMP1 did not associate with traits likely to cause lordokyphosis (any fracture and osteoporosis in the ICE-UKB data, and BMD (hip and spine measures)), BMI (both sexes and females only) or lifespan (females) in the Icelandic data." (PMID 32184442, 2020).
pelvic organ prolapse (2 papers, 2022). Abnormal descent of a pelvic organ resulting in the protrusion of the organ beyond its normal anatomical confines. "The lead SNP rs3791675 in EFEMP1 encodes an extracellular matrix glycoprotein of the fibulin family and has been associated with body height, BMI-adjusted waist circumference, pelvic organ prolapse, and BMI-adjusted WHR." (PMID 35831902, 2022). "Additionally, EFEMP1 has recently been implicated in conferring susceptibility to pelvic organ prolapse and intriguingly is also associated with anthropometric measures of height and abdominal circumference, which have also been associated with ZC3H11B." (PMID 36584111, 2022).
Stargardt disease (2 papers, 2020). "ABCA4, which harbors causative mutations leading to Stargardt disease, was enriched in foveal photoreceptors; EFEMP1, implicated in Doyne Honeycomb Dystrophy, was predominantly expressed in foveal Müller glia." (PMID 32555229, 2020).
triple-negative breast carcinoma (2 papers, 2018 to 2026). An invasive breast carcinoma which is negative for expression of estrogen receptor (ER), progesterone receptor (PR), and human epidermal growth factor receptor 2 (HER2). "Together, our results identify a CIN-associated EV program in triple-negative breast cancer and highlight EFEMP1 as a potential therapeutic target to impair EV-driven tumour cell migration." (PMID 41974939, 2026).
amyloidosis (1 paper, 2023). A disorder characterized by the localized or diffuse accumulation of amyloid protein in various anatomic sites. "Few reports on EFEMP1 focused on solid tumors and amyloidosis." (PMID 37174963, 2023).
anaplastic oligodendroglioma (1 paper, 2011). A WHO grade III oligodendroglioma with focal or diffuse malignant morphologic features (prominent nuclear pleomorphism, mitoses, and increased cellularity). "We then investigated two primary culture lines derived from a WHO grade IV GBM (GBM16B) and a WHO grade III anaplastic oligodendroglioma (OG2B), and showed that EFEMP1 knock-down promoted tumor growth starting at day 14 after s.c. implantation." (PMID 21955618, 2011).
atherosclerosis (1 paper, 2020). A disease characterized by the build-up of fatty material and calcium deposition in the arterial wall resulting in partial or complete occlusion of the arterial lumen. "However, the roles of FZD6 and EFEMP1 in atherosclerosis are still unclear." (PMID 32616722, 2020).
benign ovarian tumor (1 paper, 2013). "To evaluate the mRNA and protein expressions of EFEMP1 in ovarian tissues, we detected 260 human ovarian tissue specimens, including 40 normal human ovaries, 60 benign ovarian tumors and 160 epithelial ovarian carcinomas by immunohistochemistry and real time RT-PCR." (PMID 24236050, 2013).
benign prostatic hyperplasia (1 paper, 2017). A non-cancerous nodular enlargement of the prostate gland. "At last, we verified five methylated sites (cg06363129, cg07220448, cg11417025 in SOSTDC1; cg08843517 in CYBA; and cg05385513 in EFEMP1) in PCa and normal tissues, including adjacent tissues and benign prostatic hyperplasia (BPH) through pyrosequencing." (PMID 28938548, 2017).
biliary cirrhosis (1 paper, 2022). "In contrast, overexpressed EFEMP1 was observed in certain BA cases that had more severe biliary cirrhosis on the histopathology sections." (PMID 36114336, 2022).
bladder tumor (1 paper, 2021). "In the subgroup analysis of NMIBC, high EFEMP1-expressing NMIBCs correlated with a higher bladder tumor recurrence rate than low EFEMP1-expressing tumors (p < 0.0001)." (PMID 34204134, 2021). "In NMIBC, high EFEMP1 immunoexpression was correlated with a high bladder tumor recurrence rate." (PMID 34204134, 2021).
Bone Tumor (1 paper, 2020). "Thus, an increased circulating EFEMP1 level is not specific for OS in many primary bone tumors." (PMID 32280689, 2020).
cataract (1 paper, 2024). Partial or complete opacity of the crystalline lens of one or both eyes that decreases visual acuity and eventually results in blindness. "Future studies will clarify how EFEMP1 contributes to cataract susceptibility." (PMID 38984127, 2024).
Cholestatic liver disease (1 paper, 2018). "More specifically, the similar expression pattern of EFEMP1 in both BA and other cholestatic diseases suggests a common function for EFEMP1 in cholestatic liver disease." (PMID 30102696, 2018). "Further studies will be necessary to define the possible role of EFEMP1 in the development of BA, and in progression of fibrosis in BA or other cholestatic liver diseases." (PMID 30102696, 2018). "Our data support a role for EFEMP1 in the etiology of BA, and its possible involvement in other cholestatic liver diseases." (PMID 30102696, 2018). "This distinct expression pattern suggests that EFEMP1 may have a bile duct-specific role in cholestatic liver disease." (PMID 30102696, 2018). "Downstream expression analysis of EFEMP1 RNA and protein localization in liver specimens suggest that EFEMP1 may have functional relevance not only in BA, but also in other cholestatic liver diseases." (PMID 30102696, 2018).